FZD5 (frizzled class receptor 5)
Diseases named in the same sentence as FZD5 in open-access papers (continued):
Sharing a sentence is not in itself a finding about the gene and the disease.
non-melanoma skin carcinoma (1 paper, 2012). "Expression of Wnt5a, Fzd3, and Fzd5 in non-melanoma skin cancer." (PMID 22384081, 2012).
non-small cell lung carcinoma (1 paper, 2020). A group of at least three distinct histological types of lung cancer, including non-small cell squamous cell carcinoma, adenocarcinoma, and large cell carcinoma. "OMP-18R5 (Vantictumab) targets the FZD1, FZD2, FZD5, FZD7, and FZD8 frizzled protein receptors to block WNT signaling are being investigated in phase I clinical trials in breast, pancreatic, and non-small cell lung cancer." (PMID 32758244, 2020).
oral cancer (1 paper, 2021). "FTH1P3 pseudogene transcript was also associated with oral cancer risk and prognosis by becoming a miRNA sponge for miR-224-5p and thereby modulating the expression of the FZD5 (frizzled class receptor 5) gene, facilitating cell proliferation and colony formation." (PMID 34440428, 2021).
oral squamous cell carcinoma (1 paper, 2021). "miR-224-5p is associated with FTH1P3 and Fzd5 in oral squamous cell carcinoma (OSCC)." (PMID 34671643, 2021). "Fzd5 expression in oral squamous cell carcinoma (OSCC) is increased by FTH1-3, which acts as a ceRNA against miR-224-5p to remove repression of Fzd5 expression and induce proliferation and colony formation in OSCC cells." (PMID 34671643, 2021).
prostate tumors (1 paper, 2016). "Gene expression of FZD5, DVL3, RELA, MAPK9, CTNNB1, and SNAI1 is higher in metastatic prostate tumors as compared to primary prostate tumors." (PMID 27191743, 2016).
renal carcinoma (1 paper, 2024). A carcinoma arising from the epithelium of the renal parenchyma or the renal pelvis. "Simultaneously it has been revealed that in doxorubicin-resistant renal cancer cells, miR-124 expression was notably reduced, correlating with elevated levels of FZD5 and P-gp." (PMID 39679367, 2024). "A significant clinical exploration demonstrated that the expression levels of the Wnt ligand receptors Frizzled 5 (FZD5) and FZD8 were significantly elevated in renal carcinoma tissues." (PMID 39679367, 2024).
Shock (1 paper, 2015). The state in which profound and widespread reduction of effective tissue perfusion leads first to reversible, and then if prolonged, to irreversible cellular injury. "The levels of Wnt5a, Fzd5, total CaMKII, and phosphorylated CaMKII in the lung from rats with endotoxic shock were significantly increased when compared with the Control group." (PMID 26218875, 2015).
triple-negative breast carcinoma (1 paper, 2025). An invasive breast carcinoma which is negative for expression of estrogen receptor (ER), progesterone receptor (PR), and human epidermal growth factor receptor 2 (HER2). "Finally, in triple negative breast cancer cells, FZD5 enhanced DNA damage repair by upregulating FOXM1 in a β-catenin-dependent manner." (PMID 41286306, 2025).
cancer (36 papers, 2011 to 2025). A tumor composed of atypical neoplastic, often pleomorphic cells that invade other tissues. "DNA damage repair and chemoresistance are associated with cancer cell stem-like traits, therefore the role of FZD5 was further explored." (PMID 33311446, 2020). "Loss and gain of function studies further confirmed that FZD5 prevents cancer cell EMT." (PMID 33618713, 2021). "Further analysis of single-cell sequencing data (GSE103322) revealed higher enrichment of FZD7 in cancer cells compared to FZD5." (PMID 38246919, 2024). "Potential tumor-promoting roles of FZD5 were previously reported in various cancers, such as proliferation, invasion, angiogenesis, and chemoresistance after cancer recurrence." (PMID 37124518, 2023). "And we argue that the prolific cholesterol pool in RNF43‐mutant PDAC sustains continuous Fzd5 maturation and Wnt/β‐catenin‐dependent cancer growth." (PMID 35975457, 2022). "Antibodies against FZD5 including ipafricept and vantictumab have been shown effective on certain cancer types." (PMID 33618713, 2021). "For instance, in the interconnection among predicted target mRNAs and multiple signaling pathways, WNT7A and FZD5 regulates “Wnt signaling pathway,” “Proteoglycans in cancer,” and “Pathways in cancer”." (PMID 34557357, 2021). "The variation of Fzd5 activity between different cancers by either promoting or suppressing EMT and tumorigenesis presents an opportunity as a potential, specific drug target for both premalignant and malignant tissues." (PMID 34604862, 2021). "There was also a significant enrichment in the signaling pathway “Pathways in cancer” among the predictors of TS12 at 24h: genes frizzled class receptor 5 (FZD5) and epidermal growth factor (EGF)." (PMID 28359318, 2017). "It has been reported that the binding of WTN7a and FZD5 induces the canonical pathway, which has been related with cancer development." (PMID 22313908, 2012). "Therefore, Fzd5 crucially coalesces cholesterol metabolism and Wnt/β‐catenin signaling, and oxysterol provides new therapeutic promise in cancer treatment." (PMID 35975457, 2022). "In contrast, in endometrial adenocarcinoma FZD5 is downregulated compared to atrophic endometrium, which may suggest a tumor suppressive role in some cancers." (PMID 34604862, 2021). "FZD5 induces proliferation of cancer cells by activating β-catenin pathway." (PMID 33311446, 2020). "Besides, FZD5 antibodies also inhibited the growth of RNF43-mutant CRC-patient-derived organoids suggesting that FZD5 may be associated with RNF43 mutation across multiple cancer types, expanding the use of FZD5 antibody in cancer treatment." (PMID 29789460, 2018). "Since we previously found that Fzd5 expression in adult epidermis is restricted to the high granular layer (black arrow), indicative of an expression pattern governed by differentiation, we studied whether Fzd5 expression in cancers reflected tumor differentiation status." (PMID 22384081, 2012). "Mechanistically, FZD5 modulates the expression of ALDH1A1, a functional marker for cancer stem-like cells, in a β-catenin-dependent manner." (PMID 38539211, 2024). "Wnt/β‐catenin is a key molecular signalling regulator in a variety of human cancers and is usually triggered through the secreted Wnt ligands binding to Frizzled (FZD) receptor proteins, including FZD5." (PMID 34697900, 2021). "FZD5 interacts with WNT2-7a,b, WNT9b, WNT-10b and WNT-11 and exerts a range of influence on cancer progression." (PMID 34604862, 2021). "To assess the activity of the FZD5-specific FLAg, we used RNF43 mutant cancer cells in which Wnt-βcatenin signaling mediated through FZD5 is essential for proliferation." (PMID 31452509, 2019). "For example, genes with Motif 1 in Molecular Mechanisms of Cancer pathway include MAPK1, BRAF, SMAD2, FZD5, FZD8, NOTCH1 and LRP1, whereas genes with Motif 2 and/or Motif3 in the same pathway include LRP5, LRP6, MDM2, CTNND1, SMAD3, SMAD4 and SMAD7." (PMID 26040697, 2015).
cancer (continued). "In contrast, the WNT5A+ inflammatory fibroblast interacts with cancer cells via IL24:IL20RA and WNT5A:FZD5 pathways, which could promote cancer progression and chemoresistance." (PMID 38744958, 2024). "FZD5 is methylated early in the development of AML and FZD5 antibodies have been used to inhibit receptor activity in pancreatic and CRC cell lines, suggesting the potential for targeting FZD5 in AML and other cancers for prevention." (PMID 34604862, 2021). "Moreover, genes in the WNT, SHH, and BMP pathways such as WNT5A, FZD7, and FZD5, SHH, SMO, and GLI2 as well as BMP4 were likewise among the upregulated genes and were included in pathway of cancer gene set." (PMID 26998479, 2015). "Therefore, FZD5 and ELF3 function as putative tumor suppressors in this type of cancer." (PMID 33618713, 2021).
tumor (32 papers, 2012 to 2025). "25‐OHC treatment lessons Fzd5‐dependent Wnt/β‐catenin signaling and causes the mitigation of the tumor burden of RNF43‐mutant PDAC." (PMID 35975457, 2022). "However, Fzd5 may mediate inflammatory responses triggered by Wnt5a secreted by tumor-associated stroma or endothelial cells such as inflammatory cytokine production." (PMID 22384081, 2012). "FZD5 was reported to be regulated through the Wnt signaling pathway, affecting Paneth cell differentiation and playing a promoting role in tumor development." (PMID 39052013, 2024). "Circ_0067934 regulated the miR-1324/FZD5/Wnt/β-catenin pathway in hepatocellular carcinoma, which facilitated tumor metastasis and tumor growth." (PMID 38152652, 2023). "In RNF43‐mutant PDAC, the cholesterol level governs tumor growth through Fzd5‐mediated Wnt/β‐catenin signaling in vitro and in vivo." (PMID 35975457, 2022). "Tumor suppressor miR-212-5p was shown to inhibit tumor cell proliferation through repressing the expression of Frizzled Family Receptor 5 (FZD5)." (PMID 36483915, 2022). "The expression of miR‐212‐5p was noticeably low in tumour tissues, and FZD5 expression level was down‐regulated with the knockdown of LINC00115." (PMID 34697900, 2021). "The increased FOSL2 in CAFs plays a pivotal role in promoting angiogenesis by regulating Wnt5a, thus stimulating activation of the downstream FZD5/NF-κB/ERK signaling axis in vascular endothelial cells to fuel tumor angiogenesis VEGF-independent patterns." (PMID 33754039, 2021). "Analysis of the staining patterns of the receptors in tumor tissue showed a positive correlation between FZD5 and RYK expression (r=0.4404, p<0.001)." (PMID 29930766, 2018). "Where expressed, Fzd5 exhibited diffuse intra-tumor localisation (upper right), or at the tumor edge (middle right)." (PMID 22384081, 2012). "Fzd5 exhibited heterogenous intra-tumor distribution, being localised to intra-tumor clusters (top), weak/diffusely at the edge (bottom), or homogenously throughout (middle)." (PMID 22384081, 2012). "Fzd5 has been reported to play a critical role in a variety of tumours." (PMID 40230079, 2025). "Research has shown that ARID3B induces Wnt receptor FZD5, which is important for enhancing tumor cell adhesion and may contribute to metastasis." (PMID 40456746, 2025). "Moreover, cholesterol has been shown to enhance tumor growth through the Fzd5-mediated Wnt/β-catenin signaling pathway." (PMID 39777330, 2024). "Re‐expression of either WT Fzd5 or Fzd7 can rescue the tumor growth but Fzd5 I199A or C538A." (PMID 35975457, 2022). "FZD5 also mediates β-catenin-independent pathways to increase tumor cell motility." (PMID 33311446, 2020). "Thus, mislocalisation of RNF43(R127P) reduces RNF43-mediated ubiquitination of Fzd5, and the 3SD phosphomimetic substitution can restore the ubiquitination and tumour suppressor activity to RNF43(R127P)." (PMID 32934222, 2020). "The aim of this study was to explore the involvement of Fzd5 in vascular and perivascular biology, which might eventually serve as a foundation for future therapeutic strategies, e.g., in modulating tumor vasculature." (PMID 29845518, 2018). "In particular, ARID3B induction of the Wnt receptor FZD5 is important in increasing tumor cell adhesion, which may contribute to metastasis." (PMID 26121572, 2015). "We next studied the spatial relationship of Wnt5a, Fzd3, and Fzd5 in individual tumor samples." (PMID 22384081, 2012). "Secreted WNT5A was suggested to interact with a wide range of tumor cell-expressing receptors, such as LRP5, LRP6, FZD5, and FZD6." (PMID 40524253, 2025). "WNT2 can activate both canonical and non-canonical WNT signalling, while FZD5 and FZD9, both of which are expressed in the high-amplified tumours, activate different branches of the pathway (FZD5 the canonical pathway and FZD9 the non-canonical pathway)." (PMID 34003256, 2021).
tumor (continued). "In line with the cDNA array, the TMA also revealed that FZD5 and RYK expression levels were significantly higher in malignant tissues compared to adjacent tumor-free tissues of the same patients and also compared to BPH patients (data not shown)." (PMID 29930766, 2018). "The tumor cells adapting to brain tissue do provide several pro-angiogenic functions temporarily, e.g. in BN25 15, Plxnd1, Vangl2, Fzd2, Fzd5, and Vegfa promote patterning of blood vessels and vascular development." (PMID 25004123, 2014). "In contrast to our previous findings, where tumor‐derived WNT5A was corresponding with FZD5 and RYK receptor no interrelation of these receptors to stWNT5A was observed in this study." (PMID 33639039, 2021). "Upregulation of FZD5 and the ligand WNT7A increase tumor growth and cell adhesion." (PMID 26121572, 2015). "Notably, the tumor growth of Fzd7‐rescued Fzd5‐KO Patu8988s did not alter by cholesterol modulation." (PMID 35975457, 2022). "A positive immunohistochemical reaction for WNT10A, Fzd5, β-catenin, GSK-3ß, CacyBP/SIP, and LMP7 was observed in all studied kidneys tissues, although the intensity of immunoreaction varied between non-malignant kidney and RCC tissue samples, depending on the histological type of the tumor." (PMID 33330038, 2020). "In addition, proteins of the Frizzled family, such as FZD4 and FZD5, participate in the WNT signaling pathway and inflammatory processes in nervous tissue and are related to tumor initiation and cell proliferation of glioma cells, respectively, and can modulate tumor progression." (PMID 35784465, 2022).
infection (5 papers, 2009 to 2021). The state of being infected such as from the introduction of a foreign agent such as serum, vaccine, antigenic substance or organism. "Partial loss of Wnt pathway receptor Fzd5 or Fzd9 through RNA-mediated gene silencing significantly reduces infection, indicating activation of the pathway during infection occurs at the level of the receptor complex." (PMID 33883266, 2021). "More specifically, RNA silencing of Fzd5 or its ligand Wnt5a results in a highly significant reduction of infection, suggesting the necessity of Wnt5a-Fzd5 signaling for E. chaffeensis entry and survival." (PMID 33912170, 2021). "This demonstrates that interaction between TRP120 and Fzd5 is occurring during infection of monocytes." (PMID 33883266, 2021). "RNA silencing of the ubiquitously expressed Fzd5 and Fzd9 Wnt receptors, as well as the Wnt co-receptor LRP6 also results in reduced infection, indicating a possible role of the receptors for E. chaffeensis entry into the host." (PMID 33912170, 2021). "Since the duration of siRNA-mediated repression might not be sufficient for the 6-day study time course, stable repression of FZD5 and FZD7 was sought using lentiviral shRNA infection of targeted cells." (PMID 19874621, 2009).
bacterial infection (1 paper, 2021). "Fzd5 has been shown to participate in a phagocytosis signaling pathway that is active in bacterial infection of macrophages, so we chose to further investigate the TRP120-Fzd5 interaction as a model of TRP120 Fzd receptor binding and pathway activation." (PMID 33883266, 2021).
FZD5 also shares sentences with these, for which no sentence is quoted: adenocarcinoma (2 papers); Intellectual disability (2); amyotrophic lateral sclerosis (1); aniridia (1); Brachycephaly (1); cerebellar ataxia (1); cervical cancer (1); classical Hodgkin lymphoma (1); colon cancer (1); diabetic angiopathy (1); diabetic nephropathy (1); embryonal carcinoma (1); encephalitis (1); Familial exudative vitreoretinopathy (1); gastric adenocarcinoma (1); germ cell tumor (1); Gillespie syndrome (1); glioblastoma (1); Hypertension (1); idiopathic pulmonary fibrosis (1); intestinal tumours (1); ischemic heart disease (1); Kidney tumor (1); liver diseases (1); metastatic cancer (1); Microcornea (1); Obesity (1); oesophagal cancer (1); optic nerve coloboma (1); pulmonary arterial hypertension (1).
A further 8 diseases each share a sentence with FZD5 in 1 paper.